RNU6-113P (RNA, U6 small nuclear 113, pseudogene)
Gene: Small nuclear RNA gene on chromosome 21 (17,431,547 to 17,431,647, forward strand). Ensembl gene ENSG00000252462.
Homologues: Orthologues: chimpanzee U6 (99% identical), macaque U6 (91% identical), mouse Gm25578 (78% identical), rabbit U6 (67% identical), rat LOC120099418 (67% identical). Paralogues in human: RNU6-16P (78% identical), RNU6-1011P (77% identical), RNU6-552P (77% identical), RNU6-80P (77% identical), RNU6-820P (77% identical), RNU6-1005P (76% identical), RNU6-1020P (76% identical), RNU6-1029P (76% identical), RNU6-1187P (76% identical), RNU6-12P (76% identical), RNU6-13P (76% identical), RNU6-144P (76% identical), and 1286 more.